MMP9 (matrix metallopeptidase 9)
Diseases named in the same sentence as MMP9 in open-access papers (continued):
Sharing a sentence is not in itself a finding about the gene and the disease.
breast carcinoma (continued). "High levels of MMP-2 and MMP-9 have been related to breast cancer invasion." (PMID 29050342, 2017). "Furthermore, we demonstrated that inhibitor of TOPK or MMP9 as well as MMP9 siRNA efficiently blocked LPS-induced migration or invasion of breast cancer cell lines." (PMID 28212583, 2017). "The results of this study show that low-risk tumors had less MVD and lower VEGF, MMP-2, and MMP-9 expression levels compared with non-low-risk breast cancers." (PMID 29371992, 2017). "In addition, high expression of FOSL1 caused by rearrangement of the chromosome band at 11q12 appeared to be associated with desmoplastic fibroblastoma and directly induced MMP-1 and MMP-9 promoter activity in breast cancer progression." (PMID 28049150, 2017). "MMP-9 was found to be up-regulated in breast cancer samples." (PMID 28402272, 2017). "Low-risk breast cancers demonstrated lower MVD, VEGF, MMP-2 and MMP-9 than non-low-risk breast cancers." (PMID 29371992, 2017). "Metallothionein-2A, a member of the metallothioneins, could promote breast cancer cell invasion by increasing the expression level of MMP9." (PMID 28109307, 2017). "It is thus tempting to speculate that PKD/PKCμ contributes, together down-regulation of GSK3β and up-regulation of p42/p44-MAPK to the MDR-phenotype in breast cancer, concomitantly driving MMP-9 overexpression and thus metastasis." (PMID 29383118, 2017). "For example, our group has demonstrated that PRMT7 expression is significantly upregulated in both primary breast tumor tissues and in breast cancer lymph node metastases, identifying PRMT7 as a key player in promoting breast cancer metastatic potential through regulation of MMP9 expression." (PMID 28698590, 2017). "Studies have shown that p38MAPK promotes breast carcinoma invasion and metastasis and may regulate MMP9." (PMID 28977919, 2017). "PRMT7 upregulates expression of metalloproteinase-9 (MMP-9) in breast carcinoma cells but its role in macrophages is unknown." (PMID 28228757, 2017). "Besides myeloid cells, MMP9 is also produced by breast carcinoma cells, and knockdown of MMP9 in carcinoma cells significantly reduces tumor vasculature." (PMID 28977919, 2017). "This study demonstrates that the ethyl acetate fraction from E. humifusa Willd (EA/EuH) has a preventive effect on TNFα-induced invasive capability of highly metastatic MDA-MB-231 breast cancer cells through the inhibition of NF-κB-mediated MMP-9 gene expression." (PMID 27776550, 2016). "Moreover, gallic acid has also been shown to downregulate the AKT/small GTPase signalling pathway and MMP (MMP-2, MMP-9) expression in gastric carcinoma, osteosarcoma, glioma, cervical and breast cancer." (PMID 28933410, 2016). "Thus far, our data have established that Rab40b is required for MMP2 and MMP9 targeting to the invadopodia and for breast cancer metastasis in vitro and in vivo." (PMID 27789576, 2016). "Moreover, expression of MMP-2 and MMP-9 is upregulated in many cancer types, including lung cancer, breast cancer, and glioma, and is considered an important prognostic factor." (PMID 27081042, 2016). "Barx2 increased expression of both ESR1 isoforms, the estrogen-responsive genes (SOX5, RBM15 and Dynein), the tissue inhibitor of metalloproteinase (TIMP) genes (TIMP1 and TIMP3), and MMP-9, all of which promote breast cancer cell growth, survival, and invasion." (PMID 27533254, 2016). "For example, the expression of MMP9, MMP13 and MMP14 all correlated with poor survival in patients with breast cancer, and expression of MMP1 and MMP2 was associated with highly aggressive breast cancer that metastasizes rapidly to the lung." (PMID 26956475, 2016). "Reduction of MMP-9 expression by HMOX1 was also observed in breast cancer cells." (PMID 27829220, 2016). "It is still unclear whether Rab40b also regulates MMP2 and MMP9 targeting in other cancers or whether it is limited to breast cancer." (PMID 27789576, 2016).
breast carcinoma (continued). "Second, both ZEB1 and VEGFA may induce the production of matrix metalloproteinases (MMPs), such as MMP-2 and MMP-9, in breast cancer cells." (PMID 26882471, 2016). "In breast cancer, MMP9 was reported to be highly expressed, in contrast to MMP2." (PMID 26921265, 2016). "To test our hypothesis we have knockdown uPA and MMP9 by siRNA in breast cancer cells and examined the cellular behavior and the expression of these key EMT markers." (PMID 26906973, 2016). "Among secreted MMPs, the gelatinases MMP-2 and MMP-9 are of particular interest as they can hydrolyze major ECM components, such as gelatin and type IV collagen, and were repeatedly associated with breast cancer progression." (PMID 26883198, 2016). "To test whether Rhus coriaria inhibits breast cancer cell invasion by affecting the expression of MMP-9, we decided to examine the expression level of this protein in the conditioned medium using RCE-treated MDA-MB-231 cells." (PMID 26888313, 2016). "Interestingly, TGF-β1 is reported to induce MMP-2 and MMP-9 activity in a variety of human cancers, including breast cancer." (PMID 25658913, 2015). "To further confirm whether PinX1 regulated MMP-9 expression via the NF-κB signaling pathway in human breast cancer cells, we transfected NF-κB-p65 siRNA (Santa Cruz) into PinX1KD-MDA-MB-231 cells and PinX1KD-BT-549 cells." (PMID 25888829, 2015). "Furthermore, we demonstrated that PinX1 suppressed breast cancer migration and invasion by inhibiting the expression and activity of MMP-9 via NF-κB-dependent transcription in vitro and in vivo." (PMID 25888829, 2015). "Similarly, oleic acid promotes MMP-9 secretion in breast cancer cells through PKC, Src and EGFR-dependent pathways." (PMID 25790461, 2015). "Furthermore, we show that PRMT7 induces the expression of matrix metalloproteinase 9 (MMP9), a well-known mediator of breast cancer metastasis." (PMID 25605249, 2015). "Since PMS can target combine with MMP9 and MMP2, we assumed that PMS could suppress the growth and metastasis of breast cancer via regulating the activity of MMP9 and MMP2." (PMID 26674531, 2015). "For example, HIF-1α is able to transactivate matrix metallopeptidase 9 (MMP9) in breast cancer." (PMID 26057751, 2015). "Moreover, we identified that PinX1 inhibited the migration and invasion of breast cancer by suppressing MMP-9 expression and activity via NF-κB-dependent transcription in vitro." (PMID 25888829, 2015). "Such inhibition of MMP-9 by EGF was also observed in human breast cancer cell lines." (PMID 25897433, 2015). "Our results indicate that as a promising anti-cancer agent, PMS may inhibit growth and metastasis of breast cancer by inhibiting the activity of MMP9 and MMP2." (PMID 26674531, 2015). "Previous studies proved that high MMP-2 and MMP-9 expression can promote breast cancer invasion." (PMID 26599012, 2015). "Interestingly, recombinant BMP-4 suppressed constitutive and PMA-induced MMP-9 expression in both fibrosarcoma and breast cancer cells." (PMID 25897433, 2015). "Therefore, MMP-2 and MMP-9 are key factors in CHD1L that promote invasiveness of breast cancer cells." (PMID 26599012, 2015). "Therefore, we assumed that Slit2/Robo1 axis has effects on breast cancer brain metastasis probably by modulation of PI3K/Akt/β-catenin/MMP-9 signaling." (PMID 26400100, 2015). "We observed the positive relationship of TSP50 with p65 and MMP9 levels in breast cancer tissues." (PMID 25811800, 2015). "In the breast cancer MDA-MB-231 cells, their enhanced invasive properties, caused by the overexpression of the MT2A isoform, were associated with the increased expression of MMP-9." (PMID 25933064, 2015). "Moreover, accompanied by the increment of TSP50 protein levels in the 88 breast cancer tissues, nuclear level of p65 and expression of MMP9 markedly increased." (PMID 25811800, 2015).
breast carcinoma (continued). "To test whether increased MMP-9 production and alternative activation of macrophages were achieved by paracrine communication with breast cancer cells, we placed RAW264.7 cells in the presence of 4T1 cells for 48h using Transwells®." (PMID 26078009, 2015). "IL-17 promotes tumor proliferation, survive and metastasis by up regulating angiogenesis factors VEGF, CXCL8, MMP2 and MMP9, while at the same time, it significantly suppresses apoptosis in several human breast carcinoma cell lines, such as 4T1, MDA-MB-231 cells." (PMID 26313265, 2015). "Importantly, we significantly rescued invasion of aggressive breast cancer cells depleted of PRMT7 by the exogenous expression of MMP9." (PMID 25605249, 2015). "It has been suggested that TGF-β can cause epithelial-mesenchymal transition (EMT) via Smad pathway and its downstream effect genes, and also up-regulate plasminogen activator, MMP-2 and MMP-9, which degrade extracellular matrix, allowing for subsequent migration of breast cancer cells." (PMID 26597083, 2015). "Wu and colleagues found that MMP-9 expression was associated with LNM and suggested that MMP-9 may take part in the early progression of lymphangiogenesis and lymphatic metastasis in breast cancer." (PMID 26656588, 2015). "BMP-6 has also been shown to inhibit MMP-9 expression in breast cancer cells." (PMID 25897433, 2015). "Secretion of MMP-9 by tumour-associated macrophages is well documented (reviewed in14) and we have previously shown that plating RAW264.7 macrophages and breast cancer cells in contact in coculture altered their proteolytic profile, including increase of MMP-9 production." (PMID 26078009, 2015). "To further extend our findings in vivo, we determined whether there is a correlation of TSP50 with the activity of p65 and MMP9 in two tissue arrays of human breast cancer specimens." (PMID 25811800, 2015). "In breast cancer, MMP9 status is an important indicator of breast cancer prognosis." (PMID 25605249, 2015). "Recently, a growing body of evidence has been presented to show that SDF-1α/CXCR4 stimulation also leads to the secretion of various proteases, such as MMP-2 and MMP-9 by the breast cancer cells, which are then used to degrade the extracellular matrix, thereby facilitating cellular motility." (PMID 25753200, 2015). "Among the MMPs observed, MMP-9 seems to act as predictors for worse prognosis in breast cancer." (PMID 26270045, 2015). "However, some articles reported independently that breast cancer patients with high MMP-9 expression showed a poor prognosis." (PMID 26270045, 2015). "Our findings suggested that MMPs overexpression (especially MMP-9, MMP-2, MMPs overexpression in serum) might indicate a higher risk of poor prognosis in breast cancer." (PMID 26270045, 2015). "MMP9 has been identified as a predictive marker of breast cancer cell invasion." (PMID 25605249, 2015). "Collectively, our studies demonstrated that MMP-9 may be an effector of breast cancer progression and metastasis mediated by EpCAM." (PMID 26356670, 2015). "Furthermore, si-EpCAM-mediated invasion and metastasis of breast carcinoma cells required the downregulation of matrix metalloproteinase-9 (MMP-9) through inhibition of this signaling pathway." (PMID 26356670, 2015). "Finally, we also found that glaucine inhibits invasion and MMP-9 expression in the highly metastatic MDA-MB-231 breast cancer cell line." (PMID 25670016, 2015). "Our results demonstrate that upregulation of PRMT7 in breast cancer may have a significant role in promoting cell invasion through the regulation of MMP9." (PMID 25605249, 2015). "Moreover, FN14 has been shown to promote breast cancer cell migration, invasion and MMP9 expression." (PMID 26497551, 2015). "Furthermore, overexpression of MMP-9 in breast cancer has been shown to facilitate tumor cell invasiveness." (PMID 26588686, 2015).
breast carcinoma (continued). "In addition, dense expression pattern of fascin and MMP-9 in breast carcinoma tissues at the invasive fronts confirms their role as pathogenic factors for tumor cell invasion." (PMID 24993803, 2014). "A positive correlation could also be established between elevated levels of MMP-9 and breast cancer of high histological grade." (PMID 25151367, 2014). "Thus, the levels of VEGF and MMP-9, as a factor in parallel with tumor size, can also indicate the prognosis in breast cancer." (PMID 24944618, 2014). "Our results suggest that the autologous effects of MMP9 on the intrinsic breast cancer cell phenotype may be even more far-reaching, that MMP9 may act upstream of many genes as a master regulator of the malignant phenotype." (PMID 24811362, 2014). "The results suggested that the anticancer properties of ginsenoside Rg1 may derive from its ability to inhibit invasion and migration, and that these processes are regulated in breast cancer cells through the NF-κB-mediated regulation of MMP-9 expression." (PMID 25174454, 2014). "In this study, we addressed this hypothesis by assessing the potential effects of SL on TPA-induced cell invasion and MMP-9 expression in MCF-7 human breast cancer cells with related molecular mechanisms." (PMID 24885456, 2014). "MMP-9 mRNA and protein expression was examined by real-time reverse transcriptase PCR and immunohistochemical staining, respectively, in 41 breast cancer specimens with matched peritumoral benign breast epithelial tissue and suspicious metastatic axillary lymph nodes." (PMID 24845596, 2014). "In our opinion, MMP-9 expression could help segregate subsets of aggressive breast cancer into clinically meaningful subtypes." (PMID 25151367, 2014). "The levels of VEGF and MMP-9 were found to decrease as a result of tumor cytoreduction, thus, it was hypothesized that the levels of VEGF and MMP-9 may reflect the control of breast cancer." (PMID 24944618, 2014). "Thirty four (50.75%) out of 67 breast carcinoma samples were immunoreactive for MMP-9." (PMID 24993803, 2014). "The down-regulation of MMP-9 protein levels by bortezomib, the first proteasome inhibitor in the clinic, has been documented in lung cancer, squamous cell carcinoma, bladder carcinoma, breast cancer cells and myeloma cells." (PMID 25071016, 2014). "Interestingly, the first fully commercialized and FDA approved microarray-based multigene assay for breast cancer, MammaPrint®, does include MMP-9 among its 50 panel genes." (PMID 25151367, 2014). "In addition, CXCR7 regulated breast cancer metastasis by enhancing expression of metalloproteinases (MMP-9, MMP-2) and vascular cell-adhesion molecule-1 (VCAM-1)." (PMID 24886617, 2014). "Based on these results, it was assumed that fibroblasts may stimulate breast cancer cell metastasis and MMP-9 may effect this process." (PMID 25013462, 2014). "Hence, we can safely conclude that MMP-9 protein expression in vivo strongly supports both in silico analyses on microarray dataset as well as data gathered from analysis of breast cancer cell lines." (PMID 25151367, 2014). "Hence, MMP-9 is a potentially useful biomarker of aggressive and metastatic subtypes of breast cancer." (PMID 25151367, 2014). "Also, serum MMP-9 can be useful for denoting the development of metastasis in breast cancer patients." (PMID 24634847, 2014). "In addition, repression of NF-κB target genes, e.g., CD44 and possibly other genes (e.g., BCL-XL, cMyc, and MMP9), decreased proliferation and invasiveness of breast cancer cells." (PMID 25184276, 2014). "57% of basal-like and 50% of HER2-positive breast cancer patients expressed high levels of MMP-9." (PMID 25151367, 2014). "Stromal fibroblasts have been suggested to secrete MMP-9, which is stored and activated in tumor cells.Hence, evaluation of stromal MMP-9 expression may provide valuable information on breast cancer prognosis, especially in early carcinogenesis." (PMID 24845596, 2014).
breast carcinoma (continued). "Circulating serum galectin-3 may increase through MMP9-dependent cleavage of membrane-bound galectin-3, and this cleavage of galectin-3 by MMP9 promotes breast cancer angiogenesis and progression." (PMID 25499743, 2014). "MMP-9 expression in breast cancer tissues, benign epithelium and lymph nodes." (PMID 24845596, 2014). "Several studies suggested that MMP-13 might play a critical role in bone metabolism and even induce bone metastasis of breast cancer by activating MMP-9 and other enzymes." (PMID 25510449, 2014). "Postoperative levels of VEGF and MMP-9 were also detected in 118 breast cancer cases." (PMID 24944618, 2014). "In addition, frondoside A inhibited the invasion of breast cancer cells via its ability to decrease matrix metalloproteinase (MMP)-9 expression through inhibition of nuclear translocation and transactivation of NF-κB and AP-1." (PMID 25250309, 2014). "In contrast to its tumour-promoting effects, high-level gelatinase B/MMP-9 expression has also been reported to promote tumour regression in a breast cancer model, augmenting neutrophil infiltration and promoting tumour-associated macrophage anti-tumour activity." (PMID 24473089, 2014). "Similarly, 67.7% of breast carcinoma samples showing positive MMP-9 expression were found to have intense expression at the invasive fronts." (PMID 24993803, 2014). "The basal levels of MMP-1 and MMP-9 are increased in various breast cancer cells, including MCF7, in response to heregulin-β1 via activation of MAPK/ERK pathway and overexpression of Ets1 in ErbB2 expressing breast cancer cells increases the expression of MMP-1." (PMID 24709902, 2014). "Therefore, further larger studies are still needed to explore the direct relation of facsin and MMP-9 expression to breast cancer patients’ survival and their prognostic value within different treatment modality subsets." (PMID 24993803, 2014). "Furthermore, peritoneal elicited macrophages from mice bearing SEMA7A-silenced tumors produce significantly (p < 0.01) lower levels of angiogenic proteins, such as CXCL2/MIP-2, CXCL1, and MMP-9, compared to those from control DA-3 mammary tumors." (PMID 24550834, 2014). "Although this study suggested variation in four genes, MAP3K1, MMP9, TANK, and TLR9, may affect the risk of breast cancer, previous studies have observed associations for other genes in TLR or NFκB pathways." (PMID 23634849, 2013). "Altered expression of Twist, MMP-2 and MMP-9 proteins was observed in breast cancer tissue." (PMID 23935727, 2013). "MMP-2 and MMP-9 have been related to poor prognosis and lung metastasis in breast cancer." (PMID 24245968, 2013). "A recent study suggests that CCR9 may promote metastasis in breast cancer by enhancing cell migration, increasing matrix-metalloproteinase-9 (MMP-9) expression via CCL25 and supporting tumor cell survival in metastatic sites." (PMID 24259307, 2013). "Here, we examine the effects of a novel anti-MMP9 DNAzyme (AM9D) on breast tumor growth in the mouse mammary tumor virus-driven polyoma virus middle T oncoprotein transgenic (MMTV-PyMT) mouse model of breast cancer." (PMID 23407024, 2013). "Thus, we examined the effect of MDM2 on MMP9 expression in vitro and assessed the correlation between the two proteins using immunohistochemical analysis of human breast cancer tissue." (PMID 24236052, 2013). "In addition, we further found that SAHA inhibited the invasion and migration of breast cancer cells by inhibiting the activity of MMP-9 in vitro." (PMID 24130769, 2013). "Moreover, we further investigated the correlation between Twist and gelatinase (MMP-2 and MMP-9) expression in breast cancer." (PMID 23935727, 2013). "Interestingly, PA also suppressed invasiveness through the inhibition of expression another matrix metalloproteinase, MMP-9 in breast cancer cells." (PMID 23588713, 2013).